TLR3 (toll like receptor 3)
Diseases named in the same sentence as TLR3 in open-access papers (continued):
Sharing a sentence is not in itself a finding about the gene and the disease.
Sepsis (37 papers, 2011 to 2025). Sepsis is defined as life-threatening organ dysfunction caused by a dysregulated host response to infection. "Bruton’s tyrosine kinase phosphorylates Toll-like receptor 3 to initiate antiviral response, which facilitates recovery of cardiac dysfunction associated with sepsis." (PMID 35296647, 2022). "Although Btk initiates an antiviral response by activating TLR3, Btk aggravates the cardiac dysfunction associated with sepsis by promoting the conduction of NF-κB and NLRP3 and their downstream signals." (PMID 35296647, 2022). "Combinations of TLR-3, -7 and -9 could further improve the diagnostic potential of the prediction of sepsis development." (PMID 30890150, 2019). "Moreover, treatment with a TLR3 antibody could attenuate the tissue injury associated with gut ischemia and significantly decrease sepsis-induced mortality." (PMID 28198368, 2017). "Another study revealed that chloroquine, an inhibitor of endocytic TLRs (TLR3, 7, 8, and 9), affects survival rates in a polymicrobial sepsis model." (PMID 39482884, 2025). "Anti‐TLR3 antibodies considerably decreased sepsis‐induced mortality in animals and mitigated tissue damage brought on by intestinal ischemia." (PMID 38685971, 2024). "The severity of the sepsis disease, inflammatory cytokines, and 28‐day mortality were all positively connected with TLR3 expression." (PMID 38685971, 2024). "According to a previous study, the intestinal dysbiosis profile of a TLR4-induced sepsis animal model differs from that of a TLR3-induced intestinal injury model." (PMID 36838243, 2023). "Toll-like receptor 3 (TLR3), a crucial member of TLRs, whose absence can lead to autoimmune diseases, septicemia, chronic inflammation and cancer, among other pathological conditions." (PMID 36419829, 2022). "TLR3-activated human MSCs were also shown to more effectively reduce sepsis-induced inflammation and organ dysfunction and improve overall survival in a mouse model of polymicrobial sepsis." (PMID 34109180, 2021). "CRANDE interacts with TLR3, and both correlate with advanced disease inflammation in sepsis patients." (PMID 33867914, 2021). "Receiver operator curve analysis of TLR-3, -7 & -9 for discriminating sepsis and non-sepsis patients, the areas under the curve (AUC) were 0.82, 0.61 and 0.68 respectively." (PMID 30890150, 2019). "Median buffy coat TLR-3 mRNA levels were lower in sepsis patients compared with infection, gout and HC groups (0.26 vs 1.67 vs 1.15 vs 1.25 ng/ng B2M, p<0.05)." (PMID 30890150, 2019). "TLR3−/− mice are shown to have more survival after inducing polymicrobial sepsis and showed a maintenance of cardiac function at pre-CLP levels." (PMID 30364002, 2018). "Based on our prior studies emphasizing the adverse effects of plasma C5a and histones in the cardiomyopathy of sepsis, in TLR3- and TLR9-K.O." (PMID 30364002, 2018). "Anti-TLR3 antibody approaches have been described in other injury models such as sepsis, gut ischemia, and lung hyperoxia." (PMID 23762449, 2013). "Collectively, these data demonstrate that TLR3 works as an endogenous sensor of necrosis and a regulator of the immune response, pointing to receptor modulation as a possible adjuvant therapy for sepsis." (PMID 24302927, 2013). "Additionally, silencing CRNDE effectively suppressed the activation of TLR3 and p65 in mouse kidney tissues, suggesting that inhibition of CRNDE reduces sepsis-induced AKI by blocking the activation of the TLR3/NF-κB pathway (Sun BQ." (PMID 40657645, 2025). "The protein expression levels of four upregulated necroptosis‐related DEGs (PYGL, TNF‐α, CYLD and FADD) were significantly higher in the sepsis group than in the control group in all three cells, whereas the TLR3 level was only significantly higher in HUVEC cells." (PMID 40318009, 2025). "Moreover, previous studies have revealed that CRNDE promotes sepsis-induced renal injury through the TLR3/NF-κB pathway." (PMID 38169579, 2024).
Sepsis (continued). "TLR3−/− mice showed preserved cardiac function after sepsis." (PMID 30364002, 2018). "The harmful effects of TLR3 or TLR9 on cardiac dysfunction during sepsis have been reported." (PMID 30364002, 2018). "Previous studies have demonstrated that TLR3 and TLR9 mediate a systemic inflammatory response and contribute to cardiac dysfunction in animal models of polymicrobial sepsis, but the downstream mechanisms causing these injuries are unknown." (PMID 30364002, 2018). "In sepsis, Poly:IC can improve the immunosuppressive function of MSCs via the TLR3 pathway." (PMID 27195722, 2016). "Interestingly, administration of a TLR3 neutralizing antibody to mice reduced cecal damage induced by gut ischemia and improved survival of animals with polymicrobial sepsis when the antibody was given 6 and 24 h after CLP surgery." (PMID 24302927, 2013). "It has previously been demonstrated that TLRs such as TLR-2, TLR-3, TLR-4, and TLR-7 are highly expressed in the lung tissues of septic mice, therefore suggesting a potential role in the pathogenesis of ARDS during sepsis." (PMID 40076895, 2025). "Consistent with findings in sepsis and other cardiomyopathy models, TLR2 KO and TLR3 KO are shown to be protective, whereas TLR4 KO exacerbates cardiac dysfunction and cardiomyopathy." (PMID 39201339, 2024). "Numerous reports on sepsis highlight the importance of TLR2, TLR3, and TLR4 in cardiac dysfunction and cardiomyopathy, although their precise roles remain incompletely understood." (PMID 39201339, 2024). "For example, TLR2 is associated with systemic lupus erythematosus (SLE), sepsis, psoriasis; TLR3 with sepsis; TLR4 with SLE, sepsis, and psoriasis; TLR5 with psoriasis; TLR7 with SLE, stroke, and psoriasis; and TLR9 is involved in SLE, sepsis and psoriasis." (PMID 34203170, 2021). "The high expression of some proteins, such as TLR2, TLR3, and TLR4, have been demonstrated to play a crucial role in sepsis-induced acute injury of the lungs, kidneys, and intestine." (PMID 34938184, 2021). "For this aim we performed heart functional studies in TLR3−/− and TLR9−/−, by applying Echo-Doppler technology after sepsis, to compare their responses with the septic Wt mice." (PMID 30364002, 2018). "There were important hemodynamic differences applied by Echo-Doppler technology related to TLR3−/− and TLR9−/− mice after CLP, suggesting that both receptors have important but different contributions to cardiac performance in response to sepsis." (PMID 30364002, 2018). "We then measured the levels of proinflammatory cytokines (IL-6 and TNF), histones, and C5a in plasma from TLR3−/−, TLR9−/−, and Wt after inducing polymicrobial sepsis by CLP." (PMID 30364002, 2018). "Our data showing lower levels of proinflammatory cytokines in the K.O. mice suggest that signaling through TLR3 and TLR9 involves release of these proinflammatory cytokines during sepsis." (PMID 30364002, 2018). "We decided to study the role of TLR3 and TLR9 in the heart function during polymicrobial sepsis and proposed the role for complement C5a and histones mediating these events." (PMID 30364002, 2018). "We determined the roles of TLR3 and TLR9 in adverse events of polymicrobial sepsis, with a focus on development of septic cardiomyopathy, progression of which we have recently shown to be complement- and histones-dependent." (PMID 30364002, 2018). "IFN-β1 is produced through the TRIF-dependent pathway by TLR4 or TLR3 activation, and inhibition of IFN-β1 signaling reduces the mortality after CLP-induced sepsis." (PMID 25766838, 2015).
Sepsis (continued). "Herein, we will review the most popular agonist (TLR3, TLR5, TLR7, TLR8, TLR9) and antagonist (TLR2, TLR3, TLR4, TLR9) agents used in pre-clinical and clinical models of acute and chronic infections, including sepsis." (PMID 24302927, 2013). "Using TLR3 agonist PolyI:C to induce IRF-7 in TLR2−/− mice, we found no increase in basal Ppargc1a mRNA levels, but we did rescue the Ppargc1a response in sepsis." (PMID 21966468, 2011). "In the context of sepsis and sepsis-induced renal injury, necroptosis is predominantly initiated downstream of death domain receptors (such as tumor necrosis factor receptor(TNFR) and Fas) and Toll-like receptors (TLR4 or TLR3)." (PMID 39544947, 2024). "During physical exercise, muscle and adipose tissue produce a substance called irisin, which decreases the expression levels of TLR3, TLR4, MyD88, MAPK, and NF-kB, thereby reducing the release of pro-inflammatory factors and preventing the development of sepsis." (PMID 38049851, 2023). "Interestingly, Toll‐like receptor signalling was detected in sepsis, specifically in the brain (prefrontal cortex and hippocampus), via the upregulation of genes such as CD14, TLR1, TLR2, TLR3, TLR7, IRAK3 and IRAK4." (PMID 37731199, 2023). "Murine models of sepsis-induced ALI mimic TLR3, TLR4, TLR7 and NLRP3 activation but, unlike the human disease, also activate TLR2 and TLR9." (PMID 33672738, 2021). "The expressions of TLR2, TLR3, TLR4, and TLR7 increased in the kidneys and intestine of sepsis mice, indicating that these four cytokines could influence the effect of pro-inflammatory response during infection." (PMID 34938184, 2021). "More importantly, CRNDE can modulate the TLR3/NF-κB cytokine signaling pathway to trigger inflammation, suggesting that CRNDE may serve as a regulator in sepsis." (PMID 32471511, 2020). "We measured the levels of proinflammatory cytokines in cardiac tissue using heart homogenate to study how the absence of TLR3 or TLR9 affects the appearance of proinflammatory cytokines in the heart tissue after sepsis." (PMID 30364002, 2018). "While these data are preliminary, they indicate that TLR absence reduces plasma levels of proinflammatory cytokines, suggesting that events that “drive” the adverse consequences of sepsis are negatively affected by absence of TLR3 or TLR9." (PMID 30364002, 2018). "Based on these findings together with our results, it is possible that TLR3 or TLR4 activation increases IFN-β1, which subsequently increases TRAIL in CD8+ regulatory T cells during sepsis, finally contributing to the immunosuppressive state of sepsis." (PMID 25766838, 2015). "Moreover, the lower levels of complement C5a and extracellular histones in plasma during sepsis in TLR3−/− and TLR9−/− mice suggest that these biological markers may act as a downstream effector of TLR3 and TLR9 signaling." (PMID 30364002, 2018). "Indeed, Cavassani KA15 observed TLR3 activation during experimental polymicrobial sepsis and ischemia gut injury in the absence of an exogenous viral stimulus, and TLR3−/− mice were protected from the lethal effects of sustained inflammation." (PMID 28198368, 2017). "We extended the studies to determine how absence of TLR3 (frames (a) and (b)) or TLR9 (frames (c) and (d)) in CLP mice affects sepsis-induced appearance of plasma proinflammatory cytokines." (PMID 30364002, 2018).
prostate carcinoma (35 papers, 2007 to 2026). A carcinoma that arises from epithelial cells of the prostate gland. "In contrast, there is another report that claims that lower TLR3 expressions have been associated with prostate cancer recurrence in prostate cancer tissues compared to benign prostatic hyperplasia (BPH) tissues." (PMID 41601666, 2026). "Analysis of human prostate cancer samples revealed that 85 of 112 tumors exhibited TLR3 expression, and elevated TLR3 levels were significantly correlated with an increased risk of cancer recurrence." (PMID 41601666, 2026). "High TLR3 expression level was significantly associated with high probability of the recurrence of prostate cancer." (PMID 25101092, 2014). "Additionally, signaling by IRF-3 has been implicated in TLR3-mediated apoptosis in prostate cancer." (PMID 27092172, 2016). "In prostate cancer cells, activation of the TLR3-NF-κB/IRF signaling cascade by TRPM8 triggers a sterile inflammatory response." (PMID 41601666, 2026). "Activation of TLR3 directly induces apoptosis in human prostate cancer cells, highlighting TLR3 agonists as promising anti-tumor agents." (PMID 41601666, 2026). "TLR3 can be activated in prostate cancer cells, where it has been shown to induce apoptosis and inhibit proliferation." (PMID 41601666, 2026). "In the context of prostate cancer, Toll-Like Receptor 3 (TLR3) has been shown to play an immune surveillance role in TRAMP mice." (PMID 38316991, 2024). "A recent study showed that TLR3 overexpression in prostate cancer cells induces cancer invasion while its activation triggers apoptosis, confirming once again the double-edged sword nature of TLR3." (PMID 36982351, 2023). "Toll-like receptor 3 (TLR3) is a pro-inflammatory receptor and promoted glucose consumption and lactate release in prostate cancer cell lines via HIF-1α and extracellular activation of A2BR." (PMID 36741002, 2023). "Prostate cancer tissues exhibited higher expression levels of TLR3 than healthy tissues, which was also related to a higher probability of biochemical recurrence." (PMID 33986756, 2021). "In vitro, the prostate cancer cell lines LNCaP and DU-145 can respond to TLR3 agonists through NF-κB activation, but the more aggressive PC3 cell line cannot." (PMID 33986756, 2021). "A further study on prostate cancer models reported that stimulation of TLR3 with Poly(I:C) promoted the activation of the protein kinase C (PKC)-α/JNK-p38 pathway, with subsequent activation of caspase 8 and increase in apoptosis." (PMID 33147700, 2020). "Inhibition of proliferation and promotion of apoptosis of prostate cancer cells are observed after the activation of protein kinases by an agonist of TLR3, poly(I:C)." (PMID 32012718, 2020). "For example, it was shown to function through being regulated by inflammatory cytokines (IL-6, CCR9 and TLR3) during apoptosis, and involve in the pathogenesis of prostate cancer." (PMID 28545028, 2017). "In human prostate cancer patients, 85 in 112 prostate carcinomas samples showed positive expression of TLR3." (PMID 25101092, 2014). "TLR3 mRNA level was clearly enhanced in prostate cancer cells by stimulating with poly (I:C), which suggests a functional role of TLR3 in prostate cancer." (PMID 25101092, 2014). "A recent study in human prostate cancer cells suggests that TLR3 signaling triggers apoptosis and growth arrest of LNCaP cells partially through inactivation of the PI3K/Akt pathway." (PMID 25101092, 2014). "TLR3 activation directly triggers apoptosis of human prostate cancer cells; therefore, TLR3 agonists have potential to be developed as anti-tumor therapeutic agents." (PMID 25101092, 2014). "While the signaling mechanisms of TLRs are well characterized, they do not completely account for the contrasting effects observed in prostate cancer, where activation of certain receptors such as TLR3 suppresses tumor growth, whereas others like TLR2 enhance it." (PMID 41601666, 2026).
prostate carcinoma (continued). "To explore the mechanism involved in siRNA-induced toxicity on the two human prostate cancer cell lines, we studied the signaling pathway involving TLR3-mediated activation of interferon regulatory factor 3 (IRF3), which leads to release of IFNβ and generation of an inflammatory response." (PMID 36365241, 2022). "Interestingly, TLR3 activation in prostate cancer cell lines resulted in secretion of chemokines capable of attracting natural killer cells, granulocytes, B cells and T cells." (PMID 30824859, 2019). "TLR3 mRNA is detected in three prostate cancer cells lines including LNCaP, PC3, and DU-145." (PMID 25101092, 2014). "It has been shown that TLR3 is expressed in prostate cancer cells." (PMID 25101092, 2014). "TLR3 activation by poly (I:C) induces upregulation of miRNAs including miR-29b, -29c, -148b, and -152, which target DNA methyltransferases and leads to reexpression of oncosuppressor RARβ in prostate cancer cells." (PMID 25101092, 2014). "Paone and colleagues found that TLR3 could regulate the process of angiogenesis and apoptosis in prostate cancer cells through hypoxia-inducible factor 1α (HIF-1α) and PKC-dependent mechanism." (PMID 25101092, 2014). "In particular, TLR3 expression might be useful for prostate cancer prognosis and EPB41L3 hypermethylation for its detection." (PMID 17280610, 2007). "In prostate cancer, activation of TLR2, TLR4, and TLR9 stimulates tumor growth while activation of TLR3, TLR4, TLR5, and TLR7 suppress tumor development." (PMID 41601666, 2026). "Alternately, in prostate cancer, butyrate has been shown to accelerate tumor progression by inducing autophagy and upregulating the chemokine CCL20 through TLR3 signaling, ultimately recruiting M2-like macrophages that support immune suppression." (PMID 41597210, 2026). "Expression of TLR3 mRNA has been reported in the LNCaP, PC3, and DU145 prostate cancer cell lines, with stimulation by poly(I:C) leading to a marked increase in TLR3 transcript levels, indicating a potential functional role in tumor biology." (PMID 41601666, 2026). "On the other hand, in vitro experiments showed that SCFAs induced Toll - like receptor 3 (TLR3) activation and further induced autophagy activation in prostate cancer cells." (PMID 39703512, 2024). "In parallel, TLR3 activation-dependent HIF-α up-regulation appeared to induce changes in cell metabolism and lactate accumulation in prostate cancer cells." (PMID 33147700, 2020). "In the prostate cancer PC3 cell line, it has been illustrated that TLR3 activation promotes HIF-α expression and nuclear translocation, resulting in increased VEGF synthesis and secretion together with protection from apoptosis." (PMID 33147700, 2020). "In colorectal cancer, elevated luminal butyrate supports antitumor M1 polarization through enhanced glycolysis and ROS generation, whereas in prostate cancer, increased SCFA flux promotes M2-like macrophage recruitment and tumor progression through TLR3 signaling and autophagy induction." (PMID 41597210, 2026). "Moreover, a recent study showed that prostate cancer cells secrete the Transient Receptor Potential Cation Channel Subfamily M Member 8 (TRPM8) into extracellular vesicles, which then function as a TLR3 agonist." (PMID 41601666, 2026). "Poly I:C, a synthetic double-stranded RNA analog, activates Toll-like receptor 3 (TLR3) signaling and enhances interferon responses; however, its impact on CD274 expression in prostate cancer remains unclear." (PMID 41409271, 2025).